CRHR1 (corticotropin releasing hormone receptor 1)
Diseases named in the same sentence as CRHR1 in open-access papers (continued):
Sharing a sentence is not in itself a finding about the gene and the disease.
Anxiety (continued). "Moreover, CRHR2 might have a regulatory function in response to CRHR1 stimulation of the HPA axis or anxiety, and CRHR2 played an important regulatory role in the process of visceral pain signaling." (PMID 37435647, 2023). "Deletion of CRHR1 in Mor-Ens alleviated anxiety, depression, and impaired social interaction, while it did not affect conditioned aversion during opiate withdrawal, suggesting that CeA GABAergic and CRH connections with Mor-Ens might exert not exactly the same effects on negative effect." (PMID 34642456, 2021). "In addition, Crhr1-/- mice exhibit reduced anxiety-related behavior." (PMID 32244319, 2020). "Co-expression with fear-associated genes Crh, Crhr1, and Crhr2 across crude brain regions revealed that the metabolic receptor set correlated mostly in areas that are not often associated with anxiety, i.e., midbrain CRH expressing neurons, as present in the superior colliculus and nucleus ruber." (PMID 30210279, 2018). "Limbic CRHR1 is essential for HPA axis feedback in response to stress, but recent findings suggest that it also modulates anxiety-related behavior independently of the HPA axis." (PMID 41614899, 2026). "In our gene expression analysis, significant upregulations of Crh, Crhr1, and Crhr2 were observed in the amygdala in the CKD group, which is in accordance with the development of anxiety-like behavior." (PMID 37989901, 2024). "In our study, we applied the CRHR1 antagonist NBI30775, which has already been used in clinical trials for depression/anxiety and has shown good efficacy and safety." (PMID 32051550, 2021). "In contrast to CRHR1, the role of CRHR2 activation inthe manifestation of anxiety and depression is less clear, andthere are two theories trying to explain the CRHR2 involvement in the CRH behavioral effects." (PMID 34901719, 2021). "These shock-induced modulations of phasic response patterns were suppressed by systemic administration of antalarmin, a CRHR1 antagonist that reduces anxiety in EPM, blocks stress-induced anxiety and abolished the switch to passive behavior in our assay." (PMID 29904149, 2020). "This study aimed to investigate the effects of LB and MS models combined on classical anxiety-like behavior tasks and hypothalamic gene expression of targets related to HPA axis functioning (Crh, Crhr1, and Nr3c1)." (PMID 33304248, 2020). "The implication of CCK-like receptors in fly defense behaviors suggests that this is an anxiety-related signaling system, like GABA, serotonin, and Dh44-R1/CRHR1." (PMID 27020741, 2016). "Of the two receptors in this system (CRHR1 and CRHR2), overactivity of CRHR1 in anxiety and depression has been a consistent finding in animal studies." (PMID 22950410, 2012). "Although not surprising given the known role of CRHR1 in stress and anxiety-like behaviour, our findings are important as there is little understanding on the molecular identity of stress-responsive cells in the BLA." (PMID 39634490, 2024). "For instance, CRH, secreted from the central amygdala, binds to the basolateral amygdala CRHR1 and CRHR2 and may modulate stress-emotional memories and anxiety." (PMID 37508942, 2023). "Bioinformatic analysis showed that CRHR1 was the target of miR-34b, and the overexpression of miR-34b negatively modulated CRHR1 mRNA in the primary hypothalamic neurons, mitigating the hyperactivity of the HPA axis and anxiety-like behaviour." (PMID 34947970, 2021). "CRHR1 blockade in rodents prevented theCRH-induced anxiogenic phenotype, andin mice lacking Crhr1, the manifestation of anxiety behaviordecreased." (PMID 34901719, 2021). "Genetic disruption of the CRHR1 in mice eliminates the negative effect of morphine withdrawal, while deletion of CRHR1 in midbrain dopaminergic neurons increases anxiety-like behavior and reduces DA release in the prefrontal cortex." (PMID 34642456, 2021).
Anxiety (continued). "To do this, we sought to investigate: (i) the effects of MS and LB combined on maternal behavior; (ii) anxiety-like behavior during young adulthood in three tasks (OF, EPM and LD); and (iii) Crh, Crhr1, and Nr3c1 mRNA expression in the hypothalamus, as well as peripheral corticosterone levels." (PMID 33304248, 2020). "Crhr1/Crhr2 double knockout mice display sexually dimorphic HPA axis stress responses: female mice have decreased anxiety-like behavioral responses, whereas male mice show increased anxiety-like behavior." (PMID 32244319, 2020). "Two primary CRH receptor subtypes—CRHR1 and CRHR2—have been described in the central nervous system (CNS) according to their neuroanatomical expression patterns; with CRHR1 appearing to play a key role in mediating the CRH-elicited effects in depression and anxiety." (PMID 30719038, 2019). "The high co-expression with Crhr1 and stimulatory nature of the glucagon receptor suggest that like NPY, glucagon is a signal for a negative energy balance that affects in parallel food intake and anxiety." (PMID 30210279, 2018). "Generally, CRHR1 activation, increases anxiety-like behavior, whereas activation of CRHR2 suppresses behavioral indicators of anxiety." (PMID 26318631, 2015). "The conditional inactivation of CRHR1 within the murine forebrain demonstrated that limbic CRHR1 signaling modulates anxiety-related behavior, independent of its role in the neuroendocrine stress response via the hypothalamic–pituitary–adrenocortical axis." (PMID 26352593, 2015). "Similarly, CRHR1, the receptor for corticotropin-releasing hormone, is a key component of the hypothalamic–pituitary–adrenal (HPA) axis and plays a vital role in managing anxiety and stress responses." (PMID 40243462, 2025). "Identification of this pattern of differential methylation of the Crhr1 gene highlights brain plasticity, such that external stimuli, such as EE and CMS, are able to alter gene methylation states and subsequently induce changes in anxiety-like behaviors via chromatin remodeling protein recruitment." (PMID 35998298, 2023). "After exposure to NBI-27914, a specific corticotropin-releasing hormone receptor 1 (CRHR1) antagonist, which was correlated to trauma-induced anxiety, the rat model was observed for changes in the hypothalamic-pituitary adrenal (HPA) axis and anxiety-like behaviour." (PMID 34947970, 2021). "Although it is well established that CRH/CRHR1 signaling mediates aversive responses, including anxiety and depression-like behaviors, several recent studies have challenged this viewpoint by revealing anxiolytic and appetitive properties of specific CRH/CRHR1 circuits." (PMID 31619956, 2019). "Conversely, mice lacking Crhr1 show an impaired stress response and reduced anxiety." (PMID 29844474, 2018). "Conditional knock-out mice, which did not express CRHR1 in the forebrain, including limbic areas were exposed to early-life stress in the form of limited nesting and bedding material and showed reduced anxiety and increased exploration in the elevated-plus maze and the light-dark box." (PMID 36275850, 2022). "However, it could be relevant to the evidences that CRHR1 exhibits higher affinity to CRH than CRHR2 and the lack of CRHR1 leads to a greater influence to anxiety." (PMID 30898126, 2019). "CRHR1 is therefore fundamental in the development of the HPA axis and in the modulation of the anxiety response and behavior, but, in mice, Crhr1 is not essential for the formation of corticotrope cells or for ACTH production in basal conditions." (PMID 38927393, 2024). "Overexpression of YY1 in mouse neuroblastoma cells (N2a) was shown to enhance CRHR expression by increased promoter activity, suggesting that increased methylation at CpG1 of Crhr1 in LAB-CMS anxiety-exhibiting mice does not repress CRHR expression when YY1 expression is increased." (PMID 35998298, 2023).
Anxiety (continued). "Our results show increased Crh and Crhr1 (but not Crhr2) gene expression in the CeA in FD rats, supporting a potential role for augmented CRH signaling in the pathogenesis of depression and anxiety in this model." (PMID 33591956, 2021).
depression (109 papers, 2007 to 2026). "In other HPA axis genes, CRHR1 has been associated with depression, particularly after childhood trauma." (PMID 41440377, 2025). "We focused on the CRHR1 gene that has been related to the symptoms of depression and potentially contributes to increased risk for T2D." (PMID 38092990, 2025). "Our finding of cg03238173 (CRHR1) as a mediator of the association of ACEs and depressive symptoms aligns with previous findings examining major depression." (PMID 41440377, 2025). "Analyzing 12 SNPs of the CRHR2 and CRHR1 genes, a Japanese study revealed that the T/A haplotype of rs7209436-rs110402 is significantly associated with major depression." (PMID 40869374, 2025). "Other studies have correlated childhood trauma with suicide attempts, depression, neuroticism or alcohol abuse, moderated by the rs110402 and rs7209436 polymorphisms of the CRHR1 gene." (PMID 40869374, 2025). "Several single-nucleotide polymorphisms (SNPs) in the CRF1 receptor gene, CRHR-1, and their role in regulating adult depression in persons who had ELS in the form of child abuse were also studied." (PMID 40956392, 2025). "Dysfunctional CRHR1 variants can cause hypercortisolism, leading to serotonin dysfunction and depression, which can contribute to hyperglycemia, insulin resistance, and increased visceral fat, all of which are characteristics of T2D." (PMID 38927393, 2024). "Further work has confirmed that the CRHR1 gene is associated with depression, increasing the risk of depression after childhood trauma and the risk of suicide in males." (PMID 38927393, 2024). "For instance, CRHR1 has more than 45 disease mutations reported with a broad diversity of disease manifestations, including depressive disorders, Parkinson’s disease, irritable bowel syndrome, asthma, and fragile X syndrome." (PMID 34801547, 2022). "In another study, the same three haplotype-tagged SNPs of CRHR1—rs242939, rs1876828, and rs242941—also associate with a genetic risk for depression during pregnancy and post-partum." (PMID 32244319, 2020). "Although we cannot link these distal phenotypes to the biology of CRHR1 genetic variants, our findings point to a role of CRF1 in these depression-related cognitive processes." (PMID 29317606, 2018). "A haplotype of alleles T-A-T in a set of common polymorphisms in the gene encoding for CRF1 (CRHR1) has been associated with both depression vulnerability and alterations in cognitive functioning." (PMID 29317606, 2018). "In CRHR1, variation of the gene has been found to be a risk factor for depression after childhood maltreatment." (PMID 26808377, 2016). "CRHR1 (17q21.31) association is frequent in depression, and thus relevant to MetS, since depression is a frequent MetS-comorbidity." (PMID 27147943, 2016). "Further, variants in CRHR1 have been associated with depression, responses to antidepressants, and alcoholism." (PMID 25802844, 2015). "Polymorphisms in the CRHR1 gene have been implicated in the susceptibility for certain neuropsychiatric disorders, particularly under conditions of stress, including major depression, alcoholism and child abuse." (PMID 25954915, 2015). "Single nucleotide polymorphisms and haplotypes of CRHR1 were also found to be significantly over-represented in patients with major depression compared to controls." (PMID 26518448, 2015). "Variants in the corticotropin-releasing hormone receptor 1 (CRHR1) gene have been associated with alcoholism and depression." (PMID 25802844, 2015). "It has recently reported that variants in CRHR1 are significantly associated with depression and alcoholism." (PMID 25802844, 2015). "Previous studies have shown that polymorphisms in the coding and regulatory regions of CRHR1 gene are associated with the onset of certain neuropsychiatric disorders, including major depression, bipolar disorder, alcoholism and others." (PMID 25954915, 2015).
depression (continued). "Genetic variants in CRHR1 have been associated with anxiety disorders, major depression, and alcoholism, especially in the context of early life adverse events." (PMID 24741566, 2014). "A differential pattern of results emerged between A allele carriers and GG homozygotes suggesting that vulnerability to depression is associated with a specific CRHR1 genotype." (PMID 24596569, 2014). "CRHR1 function has been reported to be specifically associated with increased fear, alertness, depression, and anxiety." (PMID 24741566, 2014). "For instance, some reports have suggested a relationship between CRHR1 polymorphisms (rs1876828, rs242939, and rs242941) and both the risk of suffering major depression and antidepressant response to FLX." (PMID 25086452, 2014). "Polymorphisms in the CRHR1 gene have also been associated with depression and the treatment efficiency of depression." (PMID 24379738, 2013). "The aim of the current study was to examine the combined interaction of the 5-HTTLPR and CRHR1 polymorphisms with childhood abuse in predicting current symptoms of depression in a sample of over 1,000 African-American men and women." (PMID 20029939, 2010). "The genotypes and haplotypes of CRHR-1 variations may serve as potential predictors of adult depression risk and resilience in men and women with a history of child abuse." (PMID 40956392, 2025). "Furthermore, CRF activity at the CRHR-1 in extrahypothalamic areas causes anxiety and depression symptoms." (PMID 40956392, 2025). "Also, more studies are needed to integrate CRHR-1 polymorphisms and early life stress into predictive models of depression." (PMID 40956392, 2025). "As the CRH system plays a role in depression-stress response and CRH SNPs are depression risk variants, and as CRHR1 variants modulate antidepressant response, we hypothesize that CRH system resistance may lead to hypercortisolism." (PMID 38092990, 2025). "CRHR1 minor genotype was associated with a lower risk of fatigue and depression after aSAH." (PMID 32305063, 2020). "Genetic vulnerability for major depressive disorder is also been linked to the CRHR1 gene." (PMID 32244319, 2020). "CRHR1 minor genotype was associated with less fatigue and depression symptoms after aSAH." (PMID 32305063, 2020). "A polymorphism of CRHR1 was reported to be related to recurrent major depressive disorder (MDD)." (PMID 26808377, 2016). "The authors, therefore, speculate that the CRHR1 gene moderates emotional memory, which in turn may be linked to risk versus resilience against depression." (PMID 24596569, 2014). "Moreover, CRHR1 expression was significantly associated with clinical manifestations showing negative correlation with intensity of pain and stool form, as well as with psychological stress and depression symptoms." (PMID 33244004, 2020). "In addition, we hypothesized that CRHR1 blockade may reduce stress-associated behaviors previously linked to endometriosis such as anxiety and depression." (PMID 30427841, 2018). "Also, three polymorphisms in the CRHR1 gene (rs1876828, rs242939, and rs242941) were associated with major depressive disorder and with antidepressant response to FLX in Chinese patients, and better antidepressant response in a high anxiety depressed group of Mexican-Americans." (PMID 25086452, 2014). "Overexpression of CRH and CRHR1 can be regarded as the primary neurobiological correlate of major depressive disorder." (PMID 36624454, 2023). "Epigenetic changes in the body and promoter of CRHR1 have been found to be highly predictive of major depressive disorder and panic disorder in some cohorts." (PMID 34919805, 2022). "Given that more than 30% of people affected by this pathology suffer from treatment-resistant depression, the opportunity to investigate the effects of CRHR1 antagonists in this specific cohort of patients is of particular interest." (PMID 36552294, 2022).
depression (continued). "In terms of two prospective longitudinal cohort studies, the gene CRHR1 was suggested to exert a protective effect against adult depression among subjects who reported childhood maltreatment by consolidating memories of emotionally arousing experiences." (PMID 34895209, 2021). "In the restrained group, genes involved in long-term depression (Plcb4, Gucy1a3, Prkg2, Ppp1r17, Grid2, and Crhr1) were downregulated compared to the control group." (PMID 34276303, 2021). "For men an interaction effect of physical neglect with Corticotropin-releasing hormone receptor 1 gene on depression was found." (PMID 33614574, 2021). "CRHR1 genotype has been associated with PTSD and depression symptoms in survivors of post-surgical intensive care unit treatment." (PMID 32305063, 2020). "Studies have found a significant interaction between SNP rs110402 of the CRHR1 gene and the environment (childhood trauma) regarding the development of depression in adults." (PMID 32244319, 2020). "Accordingly, dysregulation of the CRH/CRHR1 system has been observed in stress-related psychopathologies including depression and anxiety disorders." (PMID 31619956, 2019). "For example, CRHR1 antagonists have been tested for the treatment of disorders including depression, irritable bowel syndrome (IBS), and proposed as a possible treatment for anxiety disorders." (PMID 30427841, 2018). "In humans, genetic variability in the gene encoding for CRF1, CRHR1, has been implicated in individual differences in vulnerability to depression and/or severity of depression." (PMID 29317606, 2018). "Since 2004, various CRHR1 antagonists have entered clinical trials for the treatment of depression, IBS, and social anxiety disorder." (PMID 28492284, 2017). "In human, there is evidence for an interaction of CRHR1 function and stressful life events on vulnerability to depression and alcoholism through regulation of HPA-axis and possibly additional interaction with serotonin transporter loci." (PMID 22950410, 2012). "While CRHR1 deficiency in the forebrain reduces stress-induced cognitive impairment, certain mutations, such as the CRHR1 TAT haplotype, are linked to cognitive dysfunction, including difficulties in decision-making, reasoning, learning, and memory in the context of depression." (PMID 41614899, 2026). "The CRHR1 gene has been studied with depression for more than a decade." (PMID 38092990, 2025). "Moreover, the use of a corticotropin-releasing hormone receptor 1 (CRHR1) antagonist has been shown to reduce oxidative stress by inhibiting the Keap1-Nrf2-p62 pathway, thereby alleviating depression-like behaviors in PSD by reducing abnormal p62 accumulation." (PMID 39655159, 2024). "CRH binds to CRHR1 (CRH receptor 1) in the hypothalamus, which is responsible for depression-like behaviour; therefore, inhibiting CRHR1 activity may provide novel psychopharmacological therapeutics for depression." (PMID 36624454, 2023). "Methylation analyses of 9 promoter/regulatory regions of genes known to be implicated in depression/PTSD (ADCYAP1, BDNF, CRHR1, DRD2, IGF2, LSD1/KDM1A, NR3C1, OXTR, SLC6A4) were performed on DNA from blood samples by the MassARRAY EpiTYPER platform, with MassCleave settings." (PMID 36001138, 2023). "Variants in the CRHR1 gene have also been shown to have a protective effect on developing depression after childhood trauma among males, but not females." (PMID 36741030, 2022). "For example, inhibition of both A2AR (adenosine 2A receptor) and the corticotrophin-releasing hormone receptor 1 (CRHR1) by inhibitors may improve cognitive function and reduce depression in AD patients." (PMID 32102186, 2020). "Regarding genetic factors, the corticotropin-releasing hormone receptor 1 (CRHR1) gene may moderate the effects of childhood trauma on depression." (PMID 30983960, 2019).